PTH (parathyroid hormone)
Diseases named in the same sentence as PTH in open-access papers (continued):
Sharing a sentence is not in itself a finding about the gene and the disease.
osteoporosis (continued). "Thus, we hypothesized that conjunctive use of PTH and ZOL exhibited a better preventive effect than PTH or ZOL alone on particle-induced implant loosening in a rat model with osteoporosis." (PMID 35546997, 2022). "This observational cross-sectional study collected the following data regarding bone health: osteoporosis and osteopenia diagnosis, lumbar spine (LS) and femoral neck bone mineral density (BMD), serum levels of 25-hydroxyvitamin D3 (25(OH)D3), calcium and parathyroid hormone." (PMID 35458148, 2022). "Since it has been reported that salubrinal regulates the differentiation of osteoclasts and osteoblasts in osteoporosis by inhibiting the dephosphorylation of eIF2α, so it was not surprising to find that salubrinal can enhance the PTH‐induced osteoblast differentiation and proliferation." (PMID 33615575, 2021). "Parathyroid hormone (PTH), an endocrine factor secreted by the parathyroid gland, has significant effects in terms of regulating bone metabolism and has been used as the only approved therapy by the Food and Drug Administration for osteoporosis in the United States." (PMID 34350461, 2021). "In addition, intermittent parathyroid hormone (PTH) treatment -an anabolic agent for bone- used for treatment of osteoporosis, fails to reduce erosion volume in patients with established RA with disease activity controlled by TNF blockers." (PMID 31001277, 2019). "This study shows that despite recent advances in the diagnosis and treatment of osteoporosis, elderly people scheduled for spinal surgery often show diminished bone mineral density, inadequate vitamin D status, elevated PTH levels and frequently have no anti-osteoporotic therapy." (PMID 29439698, 2018). "In particular, we could not adjust for bone formation (osteoporosis, fracture, and bone density), which is decreased in diabetic patients, PTH, soluble Klotho, and vitamin D status." (PMID 29996526, 2018). "Teriparatide, recombinant human N-terminal fragment of parathyroid hormone, is a bone anabolic agent shown to increase bone mass and strength and reduces the incidence of vertebral and non-vertebral fractures in post-menopausal women with osteoporosis." (PMID 24608203, 2014). "Hence, low-trauma fractures in early CKD without abnormalities of vitamin D metabolism and PTH can be diagnosed using the WHO osteoporosis criteria, a T-score of −2.5 or lower or fragility fractures, as in the postmenopausal population." (PMID 24501586, 2013). "Our result is not in agreement with the reports that raloxifene lowered serum PTH in postmenopausal women with osteoporosis and that raloxifene did not affect PTH levels in those with primary hyperparathyroidism although serum calcium decreased in both studies." (PMID 23843842, 2012). "In four patients with insufficient 25-OH Vitamin D and increased PTH there may have been some osteomalacia, but we did not differentiate osteomalacia from osteoporosis." (PMID 21812978, 2011). "Taking into account the interaction of PTH signaling with mechanical loading on bone cells, there could be an interaction between physical activity and treatment of osteoporosis with PTH fragments, but this was not studied at present in the clinic." (PMID 21209784, 2010). "PTH is approved for treatment of osteoporosis in men and women, but patients with cancer currently are not treated with PTH because of concerns that the treatment might promote tumor growth or osteosarcoma." (PMID 21188144, 2010). "Preoperative PTH levels demonstrated a small but statistically significant association with HBS development (OR 1.002 per pg/mL increase, 95% CI 1.001–1.003, p = 0.031), while osteoporosis showed a positive but non-significant trend (OR 2.05, 95% CI 0.80–5.26, p = 0.271)." (PMID 40725638, 2025).
osteoporosis (continued). "If a bone biopsy is not possible, elevated bone-specific alkaline phosphatase (BSAP) levels and intact serum PTH levels of over 350 pg/mL suggest an absence of dynamic bone disease and that treatment with an antiresorptive osteoporosis agent might be effective." (PMID 39697967, 2024). "Importantly, intermittent administration of PTH is effective for improving low bone mineral density (BMD) at the placed implant site, and for obtaining primary stability and osseointegration in cases of severe osteoporosis, such as those induced by glucocorticoid administration." (PMID 35675357, 2022). "Moreover, PTH in the OP group within the normal range ruled out secondary PTH-induced osteoporosis." (PMID 34869341, 2021). "Furthermore, we are focusing on studying the effects of I-PTH on the MCC and the subchondral bone before and after ovariectomy, as PTH is the only FDA approved anabolic drug for osteoporosis and the effects of the I-PTH on the MCC and the subchondral bone are yet not reported." (PMID 28607469, 2017). "In addition, excessive levels of endogenous PTH are not necessarily a part of the osteoporosis phenotype but have often been observed in postmenopausal osteoporosis due to vitamin D deficiency, renal insufficiency, or other causes of secondary hyperparathyroidism." (PMID 23963633, 2014). "As discussed in the inclusion criteria, in our center, we treat patients with osteoporosis and previous fractures with teriparatide only when they present with a homogeneous trend of low bone turnover in the absence of therapies that might excessively suppress PTH." (PMID 39871033, 2025). "In this study, despite the discontinuation or substitution of osteoporosis drugs during MRONJ treatment, PTH levels decreased in both groups without significant differences, indicating a need for further studies on MRONJ treatment and PTH level changes." (PMID 40217244, 2025). "Third, we did not measure serum calcium and parathyroid hormone, and we could not determine whether the association of 25(OH) D with SUA was partly mediated by calcium or secondary hyperparathyroidism, although individuals using anti-osteoporosis drugs were excluded." (PMID 32493273, 2020). "Notably, we found bone turnover markers such as PTH, osteocalcin, and alkaline phosphatase associated with an adverse cardiovascular outcome after CABG surgery at a 3-year time point regardless of osteopoenia/osteoporosis, coronary or peripheral atherosclerosis, and CAC." (PMID 31597282, 2019). "Furthermore, parathyroid hormone (PTH) and 25-hydroxyvitamin D (25OHD) have been suggested to be important hormones in the regulation of calcium and phosphorus metabolism, and thus play major roles in osteoporosis, though their relationship with BTMs remains unclear." (PMID 25117452, 2014). "Nonetheless, the presence of osteoid and elevated serum level of PTH, BGP and Opn suggest the development of osteomalacia rather than an osteoporosis." (PMID 23977109, 2013). "Furthermore, we did not use a well-established treatment of osteoporosis such as bisphosphonates, RANK ligand inhibitors, sclerostin inhibitor, and parathyroid hormone in this study." (PMID 40283112, 2025). "However, for patients with hypoparathyroidism, PTH therapy should be considered as the replacement of a missing hormone and is thus not comparable to the use of PTH1−34 to treat osteoporosis." (PMID 35485213, 2022). "Therefore, hyperparathyroidism or PTH replacement can influence both SUA and vitamin D. We excluded the subjects who took anti-osteoporosis drugs, thus, no participant used PTH replacement." (PMID 32493273, 2020). "Unlike PTH, a β-arrestin biased PTH isoform (bPTH7-34) appears to uncouple the beneficial anabolic effects of the PTH1R activation from its catabolic and calcitropic negative side effects, thus confirming an effective role for β-arrestin in osteoporosis treatment." (PMID 30546309, 2018).
osteoporosis (continued). "However, we did not observe significant differences between the ADV and non-ADV treatment groups with respect to intact serum PTH concentration, 25-hydroxyvitamin D, and urinary NTX concentration, which are important markers of hyperparathyroidism, osteomalacia, and osteoporosis, respectively." (PMID 24106611, 2013). "In addition, the persistent absence of parathyroid hormone (PTH) has long-term systemic effects on the body, such as the development of osteoporosis (due to the decreased function of osteocytes), premature cataracts, cardiac dysfunction, and neurologic dysfunction." (PMID 21197072, 2010).
vitamin D deficiency (708 papers, 2007 to 2026). A nutritional condition produced by a deficiency of VITAMIN D in the diet, insufficient production of vitamin D in the skin, inadequate absorption of vitamin D from the diet, or abnormal conversion of vitamin D to its bioactive metabolites. "BS patients often have high parathyroid hormone (PTH) due to calcium and vitamin D deficiency, which inhibits bone formation." (PMID 41733896, 2026). "Patients with vitamin D deficiency had markedly low 25(OH)D levels (mean 18.4 nmol/L) and high PTH (mean 261.7 pg/mL), consistent with secondary hyperparathyroidism." (PMID 41704483, 2026). "In multivariable analysis, higher parathyroid hormone levels, longer dialysis duration, and vitamin D deficiency were independently associated with high gland burden." (PMID 41976864, 2026). "Investigations demonstrated severe pancreatic exocrine insufficiency (PEI; faecal elastase 42 μg/g), vitamin D deficiency (25 nmol/L), and secondary hyperparathyroidism (PTH 10.8 pmol/L)." (PMID 42317587, 2026). "Vitamin D deficiency impairs active calcium absorption and thereby lowering ionized calcium and stimulating compensatory secretion of PTH." (PMID 41601890, 2026). "Prior to surgery, 99.4% of participants had vitamin D deficiencies, 40.9% had elevated Parathyroid Hormone (PTH) levels, and significant proportions had iron (47.1%), folate (32%), and vitamin B12 (13.1%) deficiencies." (PMID 39940424, 2025). "To reduce this risk, we reported both PTH and calcium outcomes at 6 and 12 months, and noted that the six normocalcemic PTH elevations at 12 months were due to vitamin D deficiency." (PMID 41323977, 2025). "The increased frequency of vitamin D deficiency and insufficiency in the general population has an impact on the estimation of the normal PTH range." (PMID 40709988, 2025). "Laboratory tests revealed elevated serum PTH levels, decreased serum phosphate, normal or elevated alkaline phosphatase, elevated serum calcium, and vitamin D deficiency." (PMID 41036144, 2025). "Despite the correction for a vitamin D deficiency (corrected to 41.0 ng/mL), her PTH level was consistently around 90 pg/mL." (PMID 40434298, 2025). "Intact PTH was also measured because high vitamin D deficiency tends to cause secondary elevation of PTH levels, even when blood calcium levels are normal." (PMID 40635068, 2025). "The role of increased PTH and vitamin D deficiency in this process further emphasizes the complex relationship between obesity and skeletal health." (PMID 40136609, 2025). "Another case involved a patient with myeloma with vitamin D deficiency who exhibited a secondary increase in PTH levels and was misdiagnosed with hyperparathyroidism." (PMID 40610015, 2025). "The relationship between circulating and locally produced vitamin D in regulating PTH synthesis is complex, with mild vitamin D deficiency possibly leading to secondary hyperparathyroidism due to reduced active vitamin D production." (PMID 41149617, 2025). "If vitamin D deficiency is found, supplementation with vitamin D (such as cholecalciferol) is advised to suppress PTH, increase serum calcium levels, and maintain the normal calcium-phosphate homeostasis through a tightly controlled feedback cycle." (PMID 41210046, 2025). "Reduced sun exposure, dietary changes, and lifestyle shifts during lockdowns have led to widespread vitamin D deficiency, which is a well-known trigger for elevated parathyroid hormone (PTH) levels." (PMID 40709988, 2025). "Of note, from the 61 patients who had low PTH levels ≤ 15 pg/mL: 6/61 (9.8%) had vitamin D deficiency and 24/61 (39.2%) insufficiency." (PMID 40709988, 2025). "Unlike previous sections that focus on RAAS-mediated sodium and potassium changes, this section will emphasize PTH dysregulation, vitamin D deficiency, and the role of cortisol in obesity-induced electrolyte disorders." (PMID 40136609, 2025).
vitamin D deficiency (continued). "In PLWHIV, factors such as cART (particularly TDF), chronic inflammation, and vitamin D deficiency can exacerbate magnesium depletion, further disrupting PTH regulation." (PMID 41295288, 2025). "Our findings showed that individuals with vitamin D deficiency exhibited a higher BMI and PTH and that serum 25(OH) D concentrations were significantly negatively related to the BMI and PTH." (PMID 40613069, 2025). "Approximately 20% of the elderly participants were found to have vitamin D deficiency accompanied by elevated PTH levels, indicating secondary hyperparathyroidism." (PMID 40709988, 2025). "This case underscores the importance of considering the impact of vitamin D deficiency on parathyroid function and recurrent PTH increase, even in patients with a history of parathyroidectomy." (PMID 40686699, 2025). "Vitamin D deficiency, an elevated parathyroid hormone (PTH), and normal serum calcium were noted on bone and metabolic panels." (PMID 40625472, 2025). "The 25-hydroxyvitamin D (25(OH)D) concentration at which parathyroid hormone (PTH) concentration plateaus has been considered to benchmark vitamin D deficiency." (PMID 40139482, 2025). "This overproduction of PTH, along with vitamin D deficiency, causes a mineral bone disorder resulting in defective bone mineralization, vascular growth, soft tissue calcification, and bone marrow fibrosis." (PMID 40244253, 2025). "Vitamin D deficiency impairs calcium absorption and leads to elevated levels of parathyroid hormone (PTH), which in turn triggers calcium resorption from the bone matrix, ultimately resulting in decreased bone mass." (PMID 40566375, 2025). "Blocking aberrant signaling through Aβ, the GABAB1R/CaSR dimer, and Tau can suppress tonic PTH hypersecretion in hyperparathyroidism associated with vitamin D deficiency." (PMID 40492090, 2025). "PTH was found to be positively correlated with IL-17 in a study that included female students with vitamin D deficiency." (PMID 40529359, 2025). "Risk factors include elevated preoperative calcium and PTH levels, large tumor size, osteitis fibrosa cystica, and vitamin D deficiency, all of which were present in this case." (PMID 41293386, 2025). "To confirm the role of APP in driving PTH hypersecretion amid vitamin D deficiency, we compared the secretory responses of parathyroid glands from PTCVdr−/− mice with or without concurrent parathyroid-specific ablation of the App gene (PTCVdr−/−App−/−)." (PMID 40492090, 2025). "Common risk factors of OP are aging, sex hormone deficiency, calcium and vitamin D deficiency, elevated parathyroid hormone (PTH) levels, genetics, and unhealthy lifestyle." (PMID 39968300, 2025). "While the work presented here reveals a new, targetable signaling pathway that drives PTH hypersecretion associated with aging and vitamin D deficiency, important study limitations must be considered." (PMID 40492090, 2025). "Patients affected by OP are more prone to develop HF because of vitamin D deficiency, elevation of parathyroid hormone (PTH) plasma levels, and increased Fibroblast Growth Factor 23 (FGF-23) activity." (PMID 39997503, 2025). "Hormonal analysis revealed an increase in the levels of PTH in Najdi lambs that had vitamin D deficiency." (PMID 40231299, 2025). "At 12 months, six patients demonstrated elevated PTH despite normal calcium levels, all of whom were found to have vitamin D deficiency, indicating that the biochemical findings were attributable to secondary causes." (PMID 41323977, 2025). "In this regard, vitamin D deficiency is the most frequent cause of high PTH levels and normal serum calcium concentration." (PMID 39582410, 2025). "Further investigation revealed severe vitamin D deficiency and elevated parathyroid hormone, consistent with nutritional rickets, which was confirmed by wrist radiographs." (PMID 40822694, 2025).
vitamin D deficiency (continued). "Four months later, she presented with diffuse bone pain, progressive gait impairment, and laboratory evidence of hypercalcemic hyperparathyroidism (PTH 130 pg/mL), severe vitamin D deficiency (25[OH]D 7 ng/mL), and hypophosphatemia (2.8 mg/dL)." (PMID 40996610, 2025). "Even in common vitamin D deficiency, it is well known that bone pathology only starts once PTH rises." (PMID 39141058, 2024). "This can be attributed to the development of secondary hyperparathyroidism in response to calcium deficiency caused by vitamin D deficiency, thereby maintaining calcium levels at the expense of parathyroid hormone-induced phosphate loss in the urine." (PMID 38646263, 2024). "The majority of subjects in the high-PTH group were vitamin D deficient, and the differences between the groups in the prevalence of vitamin D deficiency or insufficiency were highly significant (p < 0.001)." (PMID 39408619, 2024). "It is possible that compensatory mechanisms in the postpartum period overcome the effects of PTH-mediated bone loss due to vitamin D deficiency during pregnancy." (PMID 38558882, 2024). "In this regard, the markedly high preoperative PTH levels and persistent vitamin D deficiency in our case should also be considered in terms of their further contribution to persistent hyperparathyroidism caused by the failed surgery." (PMID 39444450, 2024). "Other studies have noted that vitamin D deficiency results in increased parathyroid hormone levels, which results in elevated TG and increased concentrations of vitamin D, decreasing serum PTH levels." (PMID 38956709, 2024). "In the vitamin D deficiency group, a lower proportion of males, younger age, higher BMI, worse control of glucose and lipids, lower blood calcium levels, and higher PTH levels were observed." (PMID 38590822, 2024). "It was observed that nearly one-fourth of all these individuals presented elevated PTH levels and that almost all of them exhibited vitamin D insufficiency or deficiency." (PMID 39408619, 2024). "Vitamin D deficiency is linked to poor cancer outcomes but the impact of its consequence, elevated parathyroid hormone (PTH), remains understudied." (PMID 39141058, 2024). "Vitamin D deficiency triggers increased parathyroid hormone (PTH) secretion, leading to secondary hyperparathyroidism; this is for maintaining serum ionized calcium concentration." (PMID 38892599, 2024). "Elevated PTH levels resulting from low dietary calcium or, more commonly, vitamin D deficiency contribute to heightened bone turnover and gradual loss of bone mineral content, increasing fracture risk." (PMID 38892599, 2024). "Of these two metabolites, 25(OH)D is the principal metabolite to know Vitamin D status as 1,25 (OH)2D is viewed as either in the ordinary range or increased due to a secondary increase in serum PTH due to Vitamin D deficiency." (PMID 38496123, 2024). "At a hormonal level, indoxyl sulfate aggravates vitamin D deficiencies and induces skeletal resistance to parathyroid hormone (PTH)." (PMID 39684683, 2024). "37.5% of patients with insufficient vitamin D levels had normal PTH levels and 67.24% of patients with vitamin D deficiency had normal PTH levels, while only 31.0% of them had a high PTH level." (PMID 38982537, 2024). "Obesity can result from altered gene expression or the regulation of parathyroid hormone, calcium, and leptin levels due to vitamin D deficiency." (PMID 39100945, 2024). "Lastly, several studies suggest that COVID-19 is associated with impaired PTH secretion, especially in the context of vitamin D deficiency." (PMID 39355148, 2024). "High-turnover bone disease is characterized by excessive bone resorption due to elevated PTH levels, often resulting from phosphate retention and vitamin D deficiency." (PMID 39697967, 2024).